DLL4 (delta like canonical Notch ligand 4)
Diseases named in the same sentence as DLL4 in open-access papers (continued):
Sharing a sentence is not in itself a finding about the gene and the disease.
tumor (continued). "The positive rate of DLL4 expression was higher in NSCLC tissues (54.0%, 102/189) than that in the control non-tumor tissues (7.9%, 15/189; P <.001)." (PMID 30593175, 2018). "Our findings thus demonstrated that VM, Notch4, DLL4, and KAI1/CD82 were reliable biomarkers for NSCLC, and especially in predicting tumor metastasis and prognosis." (PMID 30593175, 2018). "In our study, multivariate analysis showed that VM, expression of Notch4, DLL4, and KAI1/CD82, as well as TNM stages, tumor size, DM, and LNM, were independent prognostic factors for NSCLC patients." (PMID 30593175, 2018). "Dual targeting of DLL4 and VEGF, using the bispecific antibody HD105, inhibits tumor progression of lung adenocarcinomas and gastric cancers." (PMID 30087852, 2018). "Overall, our findings indicate that complex interrelationships between the VM, Notch4, DLL4, and KAI1/CD82 in tumor progression." (PMID 30593175, 2018). "Multivariate analysis demonstrated that VM+, Notch4+, DLL4+, and/or KAI1/CD82+ specimens, and tumor size, LNM, distant metastasis (DM), and TNM stage, were independent prognostic factors for NSCLC." (PMID 30593175, 2018). "Tumor growth is dependent on angiogenesis, a biological procedure that relies on the expression of proangiogenic factors (e.g., VEGF-A and Dll-4), as well as the “tip and stalk” procedure." (PMID 30111989, 2018). "Notch4 (a marker of Notch signaling pathway receptors), DLL4 (a marker of Notch signaling pathway ligands) and KAI1/CD82 (a suppressor gene of tumor metastasis) are all effective predictive factors for tumor metastasis." (PMID 30593175, 2018). "Here, we investigated a new mechanism by which gal-3 affects tumor angiogenesis by altering the balance of JAG1 and DLL4 expression and function in ECs." (PMID 28533486, 2017). "In these xenografts, we found that more than 50% of the vessels in DLL4-overexpressing xenografts showed a strong FABP4 expression compared with 10–20% of the vessels in the control (empty vector, EV) tumours (P<0.00001)." (PMID 27568980, 2017). "We concluded that DLL4 and JAG1 promote tumour growth by modulating tumour angiogenesis via different mechanisms." (PMID 28445154, 2017). "Expression of endogenous DLL4 in the vessels was diminished with DBZ treatment in EV-tumours and mJAG1-tumours (IV and VI)." (PMID 28445154, 2017). "Altogether, we propose a model to depict the role of DLL4 and JAG1 in tumour angiogenesis and growth." (PMID 28445154, 2017). "More importantly, the dysregulation of DLL4 seems to be common in all cells including LFS and tumor tissues." (PMID 27542210, 2016). "While overexpression of Dll4 was shown to promote tumor growth, overexpression of a soluble DSL domain of Dll1 resulted in reduced tumor growth by attenuating vascularization." (PMID 26713603, 2016). "The up-regulated NOTCH ligand Delta 4 (DLL4) is stimulated by VEGF and plays a role in tumor progression also predicting bad outcome." (PMID 26901863, 2016). "Notch-Dll4 protein interaction inhibition was also achieved by use of a soluble Dll4 ECD fused to an Fc tag (Dll4-ECD-Fc) in two separate studies, this approach phenocopied effects on tumour angiogenesis seen with the antibody blocking strategy." (PMID 26620208, 2016). "The increase in Dll4 level was confirmed in clinical specimens of HCC lesion, in comparison with non-tumor lesions." (PMID 26766040, 2016). "DLL4 is abrogated in all the LFS cells and drastically down-regulated in breast (MCF7) and brain (IMR32) cancer cells and tumor tissue samples." (PMID 27542210, 2016). "Blocking both Dll4/Notch and VEGF pathways synergistically inhibits tumor growth, which indicates the potential application of Notch inhibitors as new adjuvant chemotherapy reagents." (PMID 25723392, 2015). "To further characterize what conditions tumor were sensitive and resistant to anti-angiogenesis therapies, we compared the expressions of VEGF, CD34, and DLL4 density in the two groups." (PMID 24931473, 2014).
tumor (continued). "Our results suggest a significant tumour response in animals treated with USMB combined with radiation, and Dll4 mAb, leading to a synergistic tumour growth delay of up to 24 days." (PMID 24736631, 2014). "In summary, the results demonstrated an enhanced tumour response when ultrasound-stimulated microbubble therapy and XRT were combined with Dll4 mAb as a maintenance therapy." (PMID 24736631, 2014). "Tumours were treated with permutations of radiation, ultrasound-stimulated microbubbles (USMB) and Dll4 monoclonal antibody (mAb)." (PMID 24736631, 2014). "Tumours treated with XRT and continued Dll4 mAb therapy demonstrated a significant and synergistic tumour growth delay of 14 days (p<0.05)." (PMID 24736631, 2014). "The correlation between Dll4 expression levels and VEGFR-2 expression levels, tumor stage, tumor grade and metastasis, was examined by χ2 test and multivariate logistic regression." (PMID 25364440, 2014). "The results indicate that Dll4 blockade followed by USMB and radiation produces a synergistic tumour growth delay greater than when radiation is combined with Dll4 mAb alone." (PMID 24736631, 2014). "Next, we examined the effects of combined Dll4 and VEGF blockade on tumor vascular function using contrast-enhanced MRI." (PMID 25393540, 2014). "The aim of this study was to explore the effects of Dll4 antibody therapy alone and in combination with approved VEGF inhibitors on tumor growth and perfusion in patient-derived xenograft (PDX) ccRCC models." (PMID 25393540, 2014). "One such vascular–specific factor is DLL4, which collaborates with vascular endothelial growth factor (VEGF) to initiate important cascades that control tumor angiogenesis and tumor progression." (PMID 24931473, 2014). "Combination treatment of anti-Dll4 antibody with either anti-VEGF agent resulted in reductions in tumor perfusion and markedly increased tumor necrosis compared to single agents." (PMID 25393540, 2014). "Growth curves followed similar trends for the tumour growth treated with XRT alone, Dll4 mAb alone, and the USMB+XRT treatment." (PMID 24736631, 2014). "Tumours were grown in the hind leg of mice and treated with permutations of radiation, USMB and Dll4 monoclonal antibody (mAb)." (PMID 24736631, 2014). "Ample data in the literature indicate that Dll4 signaling plays a critical role in tumor angiogenesis and possibly in mediating resistance to anti-VEGF therapies, thus providing rationale for combined VEGF and Dll4 inhibition." (PMID 25393540, 2014). "In summary, DLL4/Notch/Hey1/MMP9 cascade mediates a direct interplay between endothelial cells and tumor cells, which eventually promotes RCC hematogenous metastasis." (PMID 24931473, 2014). "The results revealed that the tumor size, MVD, and DLL4 density were correlated with hematogenous metastasis." (PMID 24931473, 2014). "Delta-like ligand 4 (DLL4)-Notch signaling plays a key role in tumor neovascular development and angiogenesis during tumor growth." (PMID 23898884, 2013). "Thus while the importance of the Dll4-Notch1 signaling axis in tumor angiogenesis is well documented, whether Notch4, primarily expressed in the endothelium, is required for angiogenesis, vascular perfusion, and tumor progression is unknown." (PMID 23601498, 2013). "To determine the function of DLL4 during tumor angiogenesis in the SIRT1 transgenic mice, we decreased the DLL4 level present in a murine tumor model using an anti-DLL4 monoclonal antibody." (PMID 23028940, 2012). "Taken together, our data suggests that Dll4 expression by BM-VPC affects their communication with tumor vessel endothelial cells, thereby modulating tumor angiogenesis by affecting vascular stability." (PMID 21483741, 2011). "Further studies are warranted to elucidate EphrinB2 function during tumor angiogenesis, particularly in the context of anti-VEGF and/or anti-Dll4 combination therapies." (PMID 21923938, 2011).
tumor (continued). "Significantly, enhanced anti-tumor effects in preclinical models have been observed by combined inhibition of Dll4 and VEGF, and blockade of Dll4 was found to have potent growth inhibitory effects on some tumors that are resistant to VEGF inhibition." (PMID 21923938, 2011). "In vivo, we observed that reduction of Dll4 expression on BM-VPC, and subsequent transplantation into tumor bearing mice, decreased tumor vessel stabilization resulting in the formation of unstable vessels." (PMID 21483741, 2011). "While significant safety concerns have been raised in recent preclinical studies, the full therapeutic potential of targeting DLL4/NOTCH1 should be further explored given its remarkable impact on the tumor vasculature and tumor growth in preclinical models." (PMID 21824400, 2011). "Our results demonstrate that BM-VPC are activated during tumor growth by SDF1 and VEGF resulting in increased Dll4 expression." (PMID 21483741, 2011). "Taken together, Dll4 expression on BM-VPC is able to activate mature EC, which strongly suggests the cross-talk between these 2 cell types is crucial for adequate tumor angiogenesis." (PMID 21483741, 2011). "Disruption of Dll4 signaling by overexpression or inhibition of Dll4 may impair angiogenesis and blockade of Dll4-Notch signaling results in an increased density of nonfunctional vasculature and is associated with a reduction in the growth of human tumor xenografts." (PMID 20569499, 2010). "We have previously reported that the VEGF-A/Dll4/active Notch4/ephrine B2 cascade promotes liver vessel anomalies in HCC and that Notch4 is only expressed in tumour sinusoidal ECs." (PMID 21528105, 2010). "Quantitative RT-PCR was used to analyze RT2 Dll4+/+ and RT2 Dll4+/- tumors for putative differences in the expression of genes known to be involved in physiological and tumor angiogenesis." (PMID 21092311, 2010). "sEphB4-Alb mediated inhibition of Ephrin-B2/EphB4 signaling also results in areas of hypoxia in the tumor and increased expression of VEGF and Dll4, which support the combined use of Ephrin-B2, VEGF, and Dll4 inhibitors." (PMID 21092311, 2010). "To assess the effect of impaired signaling through the Dll4/Notch pathway in an autochthonous tumor model, we crossed RT2 transgenic mice with Dll4+/- mice and compared tumor burden between RT2 Dll4+/+ and RT2 Dll4+/- offspring." (PMID 21092311, 2010). "Delta-like ligand 4 (Dll4) is a Notch ligand that is upregulated by hypoxia and vascular endothelial growth factor-A (VEGF-A) and is reported to have a role in tumor angiogenesis." (PMID 19844231, 2009). "Hypoxia within the tumor microenvironment induces hypoxia-inducible factor-1α (HIF-1α), which promotes aberrant angiogenesis by upregulating vascular endothelial growth factor (VEGF) and, subsequently, delta-like ligand 4 (DLL4) in endothelial cells." (PMID 41683994, 2026). "According to a study, blockage of Dll4 inhibited tumor growth by promoting non-productive angiogenesis." (PMID 36910471, 2023). "Hypoxia-induced up-regulation of Dll4 and Hey repressed COUP-TFII (known as a regulator of vein identity) in endothelial progenitor cells, which may contribute to tumor angiogenesis." (PMID 36798826, 2023). "DLL4 is expressed in the vascular endothelium of ccRCC which on one hand activates VEGF thereby promoting angiogenesis and on the other hand activate Notch signalling in tumor cells thus inducing hematogenous metastasis." (PMID 37970211, 2023). "We recently reported that Dll4 expression on the host TME rather than on tumor cells determines the EPR or enhanced permeation and retention effect in breast tumor xenografts and thus governs nanomedicine delivery and therapy response." (PMID 36900252, 2023). "Tumor angiogenesis initiation and development is mainly governed by angiogenic growth factors, such as vascular endothelial growth factor (VEGF), epidermal growth factor (EGF), fibroblast growth factor (FGF), and delta-like 4 (DLL4)." (PMID 35681234, 2022).
tumor (continued). "The combination of specific DLL4 blockade and ionizing radiation impairs tumor growth by promoting nonfunctional tumor angiogenesis and extensive tumor necrosis." (PMID 35332121, 2022). "A study found that SELENBP1 could inhibit angiogenesis by binding with Dll4 and antagonizing the Dll4/Notch1 signaling pathway in CRC, which made SELENBP1 a potential tumor suppressor." (PMID 36286020, 2022). "Increased expression of delta-like ligand 4 (DLL4), another IRG in our study, has been observed in many tumor types and may be related to worse outcomes." (PMID 36193311, 2022). "It has been reported that the Notch signaling pathway is highly interacted with the VEGF pathway: VEGF induces DLL4/Notch signaling at several levels, while Notch signaling regulates the VEGF pathway, leading to the formation of embryonic vascular development and tumor angiogenesis." (PMID 35449809, 2022). "We validated the topological descriptors on data from studies in which tumors were treated with different agents with known effects on tumor vasculature: vascular targeting agents DC101 and anti-Dll4 in the intravital data and bevacizumab in the ultramicroscopy data." (PMID 35687679, 2022). "Interestingly, a subcluster of Endo-1 was found almost exclusively in the tumor compartment, preferentially expressing known endothelial tip cell genes (KCNE3, DLL4, EDNRB, ANGPT2, and SERPINE1)." (PMID 36180422, 2022). "In addition to VEGF, ESM1 promoted MMP9, DLL4, and ICAM3 expression, indicating that ESM1 cooperated with VEGF to promote tumor development and promote bevacizumab resistance." (PMID 36428773, 2022). "The balance of DLL4 and JAG1 endothelial expression is important for tumor vasculature generation." (PMID 35332121, 2022). "MPDZ modulates DLL4-induced Notch signaling in the vasculature through physical interaction with DLL1 and DLL4, assisting their interaction with the adherents junction protein Nectin-2 and improving Notch signaling activity with tumor angiogenesis drop off." (PMID 34440260, 2021). "Overexpressed of DLL4 can increase the production of nonfunctional blood vessels, resulting in poor tumor metastasis." (PMID 34476005, 2021). "REGN421 (enoticumab) is a human IgG1 monoclonal antibody, which can inhibit the Notch signal pathway via binding to DLL4; it was observed to inhibit tumor growth by the formation of non-functional capillaries in ovarian tumor xenograft models." (PMID 34638298, 2021). "Therefore, simultaneously targeting DLL4 and VEGF would possibly bypass this resistance mechanism and augment the anti-tumor effects of DLL4 inhibitors." (PMID 34922633, 2021). "Indeed, simultaneous blockade of DLL4 and VEGF by bispecific antibodies HD105 and HB32 showed potent anti-tumor and anti-angiogenic activity in vivo and in vitro." (PMID 34680255, 2021). "Mechanistically, DLL4 inhibition increased angiogenic sprouting, but led to non-productive blood vessel formation and diminished tumor growth." (PMID 34124039, 2021). "In addition, other investigators identified a critical role of DLL4/NOTCH1 interactions as well as a crosstalk of the Notch and VEGF pathways in tumor angiogenesis." (PMID 34124039, 2021). "Inhibition of DLL-4 promotes nonproductive angiogenesis and tumour necrosis, effectively inhibiting tumour growth, which was demonstrated in several in vivo models of cancer." (PMID 32575680, 2020). "The importance of the NOTCH1/HES1/DLL4/VEGFA/MMP13 axis in cholangiocarcinogenesis was confirmed in a collection of human iCCA tumor patients, paving the path for further investigations into the role of these genes in this tumor type." (PMID 32042099, 2020). "Moreover, MEDI0639 is a monoclonal antibody that specifically binds to DLL4 and prevents its interaction with Notch receptors, thereby inhibiting Notch-mediated signaling and target gene transcription, which may block tumor angiogenesis and eventually tumor cell growth." (PMID 32626705, 2020).
tumor (continued). "Another study demonstrated that targeting stromal cell-derived, but not tumor-derived, Dll4 reduces ovarian xenograft tumor volume." (PMID 33198378, 2020). "Preferential expression of Jagged1 and Jagged2 ligands, but not Dll1 and Dll4, was detected in tumor-infiltrating MDSCs." (PMID 33585446, 2020). "DLL4 was mainly expressed on tumor blood vessels rather than tumor cells in this xenograft tumor and colocalized with CD31-positive tumor vessels." (PMID 33383646, 2020). "Based on the results of immunohistochemical analysis of tumor blood vessels, the expression levels of VEGFR-2 and DLL4, dual targets of ABL001, were markedly reduced in tumor endothelial cells after ABL001 treatment compared to that of CD31, a conventional endothelial cell marker." (PMID 33383646, 2020). "The suppression of DLL4-Notch pathway prevents the development of tumour through the facilitating non-productive angiogenesis and preventing tumour vasculature." (PMID 33396266, 2020). "Delta-like ligand 4 (DLL4), one of the ligands of Notch receptors, is predominantly expressed in the endothelial cells and has been shown to play a pivotal role in regulating tumor angiogenesis." (PMID 31996265, 2020). "Intriguingly, the NOTCH pathway-inactive tumor cells following stimulation with DLL4 (a delta-like ligand 4) gave rise to NOTCH pathway-active cells lacking NE markers." (PMID 31827074, 2019). "Furthermore, we elucidate additional targets of FKBPL such as DLL4 and Notch 4, which in addition to CD44, are potentially involved in the multiple anti-tumour effects of FKBPL and its therapeutic peptide derivatives." (PMID 30975104, 2019). "Altogether, the results point to a functional axis of DLL4/DLL1 and Notch1/Notch2 as an essential element in DC-T-cell interactions needed for the induction of effector T-cell differentiation and eliciting T-cell-mediated anti-tumor immunity." (PMID 30940183, 2019). "Combination of DLL4-blockade by either Dll4-Fc or anti-DLL4 antibodies (REGN1035, REGN421) with VEGF-trap Aflibercept showed stronger efficacy in reducing tumor burden compared to monotherapy, by blocking angiogenesis and eliciting cancer cell apoptosis in murine tumors." (PMID 29462871, 2018). "Microvessel density was significantly higher in MpdzΔEC compared to Mpdzfl/fl mice, whereas vessel coverage was not altered, similar as observed after blocking Dll4-induced Notch signaling in the tumor vasculature." (PMID 29620522, 2018). "VM and the expression of Notch4, DLL4, and KAI1/CD82 represent promising markers for tumor metastasis and prognosis, and maybe potential therapeutic targets for NSCLC." (PMID 30593175, 2018). "Studies with mouse tumor cells however, have shown that overexpression of endothelial specific-DLL4/NOTCH signaling in Lewis lung carcinoma xenografts reduces primary tumor growth by reducing VEGF-induced endothelial proliferation, tumor vessel density and overall tumor blood supply." (PMID 30087852, 2018). "The relevance of the cooperation between VEGF and Dll4-mediated Notch signaling is highlighted by the fact that blocking of Notch signaling through Dll4 neutralizing antibody increases sensitivity to anti-VEGF therapy and reduces tumor growth." (PMID 30154786, 2018). "When expressed in tumor cells, Dll4 also functions as a negative regulator of tumor angiogenesis; however, there is no consistent information on the effects of Dll4 over-expression on tumor kinetics." (PMID 28288569, 2017). "Our results highlighted the importance of Dll4 angiogenic and epithelial effect during intestinal ApcMin/+ tumor initiation and development rather than in maintaining the normal gut homeostasis." (PMID 28086833, 2017). "Perhaps, expression of DLL4 and/or JAG1 in different cell types such as ECs, tumour cells or other stromal cells might have different effects due to the lateral inhibition." (PMID 28445154, 2017).